HLA-DPA1 (major histocompatibility complex, class II, DP alpha 1)
Description:
Binds peptides derived from antigens that access the endocytic route of antigen presenting cells (APC) and presents them on the cell surface for recognition by the CD4 T-cells. The peptide binding cleft accommodates peptides of 10-30 residues. The peptides presented by MHC class II molecules are generated mostly by degradation of proteins that access the endocytic route, where they are processed by lysosomal proteases and other hydrolases. Exogenous antigens that have been endocytosed by the APC are thus readily available for presentation via MHC II molecules, and for this reason this antigen presentation pathway is usually referred to as exogenous. As membrane proteins on their way to degradation in lysosomes as part of their normal turn-over are also contained in the endosomal/lysosomal compartments, exogenous antigens must compete with those derived from endogenous components. Autophagy is also a source of endogenous peptides, autophagosomes constitutively fuse with MHC class II loading compartments. In addition to APCs, other cells of the gastrointestinal tract, such as epithelial cells, express MHC class II molecules and CD74 and act as APCs, which is an unusual trait of the GI tract. To produce a MHC class II molecule that presents an antigen, three MHC class II molecules (heterodimers of an alpha and a beta chain) associate with a CD74 trimer in the ER to form a heterononamer. Soon after the entry of this complex into the endosomal/lysosomal system where antigen processing occurs, CD74 undergoes a sequential degradation by various proteases, including CTSS and CTSL, leaving a small fragment termed CLIP (class-II-associated invariant chain peptide). The removal of CLIP is facilitated by HLA-DM via direct binding to the alpha-beta-CLIP complex so that CLIP is released. HLA-DM stabilizes MHC class II molecules until primary high affinity antigenic peptides are bound. The MHC II molecule bound to a peptide is then transported to the cell membrane surface. In B-cells, the interaction between HLA-DM and MHC class II molecules is regulated by HLA-DO. Primary dendritic cells (DCs) also to express HLA-DO. Lysosomal microenvironment has been implicated in the regulation of antigen loading into MHC II molecules, increased acidification produces increased proteolysis and efficient peptide loading.
Synonyms: HLA-DP1A; HLASB; DP(W3); DP(W4); DPA1; HLA-DPA; HLADP; PLT1
Tractability: Small molecule: a structure with a bound ligand is known. Antibody: its Gene Ontology location is reachable by antibodies, with high confidence; UniProt places it where antibodies can reach, with medium confidence; UniProt predicts a signal peptide or a membrane-spanning region. PROTAC: ubiquitination databases record sites on it.
Safety:
Unwanted effects reported when the protein is acted on. In parentheses: how it was acted on, where the effect was seen, and who reports it.
asthma (source: ClinPGx)
Gene: Protein-coding gene on chromosome 6 (33,064,569 to 33,080,781, reverse strand). Ensembl gene ENSG00000231389.
Subcellular location: Cell membrane; Endoplasmic reticulum membrane; Golgi apparatus, trans-Golgi network membrane; Endosome membrane; Lysosome membrane
Subcellular location (Human Protein Atlas): Vesicles
Pathways (Reactome):
Immune System: Co-inhibition by PD-1; Downstream TCR signaling; Generation of second messenger molecules; Interferon gamma signaling; MHC class II antigen presentation; Phosphorylation of CD3 and TCR zeta chains; Translocation of ZAP-70 to Immunological synapse
Gene Ontology:
Molecular function: peptide antigen binding; protein binding; MHC class II protein complex binding; MHC class II receptor activity
Biological process: antigen processing and presentation of exogenous peptide antigen via MHC class II; cellular response to type II interferon; positive regulation of T cell activation; positive regulation of T cell proliferation; positive regulation of type II interferon production; immune response; peptide antigen assembly with MHC class II protein complex; positive regulation of immune response; antigen processing and presentation
Cellular component: cell surface; MHC class II protein complex; clathrin-coated endocytic vesicle membrane; endocytic vesicle membrane; ER to Golgi transport vesicle membrane; Golgi membrane; late endosome membrane; lumenal side of endoplasmic reticulum membrane; lysosomal membrane; plasma membrane; trans-Golgi network membrane; transport vesicle membrane; endoplasmic reticulum membrane; endosome membrane; Golgi apparatus; membrane
Genetic constraint (gnomAD): Loss-of-function variants: 18 observed, 20.91 expected, observed/expected ratio (o/e) 0.86, 90% interval 0.59 to 1.28. The upper end of that interval is the gene's LOEUF score, 1.28, which puts it in group 5 of 6, group 1 being the genes least tolerant of losing a copy. Missense variants: 270 observed, 330.07 expected, observed/expected ratio (o/e) 0.82, 90% interval 0.74 to 0.9. Synonymous variants: 120 observed, 134.49 expected, observed/expected ratio (o/e) 0.89, 90% interval 0.77 to 1.04.
Homologues: Orthologues: chimpanzee HLA-DPA1 (96% identical), macaque Mamu-DPA1 (94% identical), macaque MAMU-DPA (94% identical), rat RT1-Ha (63% identical). Paralogues in human: HLA-DRA (58% identical), HLA-DQA1 (55% identical), HLA-DQA2 (54% identical), HLA-DOA (53% identical), HLA-DMA (27% identical), HLA-DQB1 (22% identical), HLA-DQB2 (21% identical), HLA-DRB1 (21% identical), HLA-DMB (21% identical), HLA-DPB1 (21% identical), HLA-DRB5 (20% identical), HLA-DOB (19% identical), and 1 more.
Diseases named in the same sentence as HLA-DPA1 in open-access papers:
HLA-DPA1 is named in the same sentence as 115 diseases in open-access papers, as found by Europe PMC text mining. Sharing a sentence is not in itself a finding about the gene and the disease. The quoted sentences say what the papers report.
COVID-19 (11 papers, 2020 to 2025). A disease caused by infection with severe acute respiratory syndrome coronavirus 2. "Among the class I genes, HLA-A, -B, and -C were associated with COVID-19 severity, among the class II genes, HLA-DPA1, -DPB1, -DQB1, -DRB1." (PMID 39684907, 2024). "In contrast, downregulation of genes encoding HLA class 2 (HLA-DRA, HLA-DPA1, HLA-DMA, DYNLL1) was found in COVID-19 ECs which was further confirmed by GSEA analysis." (PMID 37029220, 2023). "Expression levels of major histocompatibility complex class II molecules, including HLA-DRA, HLA-DRB5, HLA-DPA1, and HLA-DQB1, which are expected to be increased following MAC activation in the COVID-19 group, were found to decrease." (PMID 38441496, 2024). "Differential expression analysis in the scRNA-seq revealed that MHC class II genes, such as HLA-DRB5, HLA-DPB1, HLA-DPA1, HLA-DRB1, and HLA-DRA, were downregulated in convalescent COVID-19 individuals." (PMID 35464396, 2022).
chronic hepatitis B (7 papers, 2011 to 2022). "Intronic SNP rs3077 (HLA-DPA1 gene) has been recently associated to chronic Hepatitis B (P-value = 2E-61) on a Japanese cohort." (PMID 23844243, 2013). "HLA-DPA1*01:03 and HLA-DPB1*13:01 were previously shown to be significantly associated with chronic hepatitis B in the Thai population with protective and susceptibility effects, respectively." (PMID 35769989, 2022). "The HLA-DQB1*06:09 and HLA-DPA1/DPB1 alleles which we reported here, have been detected to be associated with chronic hepatitis B with similar tendencies in previous reports in different ethnic groups." (PMID 35769989, 2022). "In 2009, significant associations between chronic hepatitis B (CHB) and a region including HLA-DPA1 and HLA-DPB1 were identified using 786 Japanese individuals having CHB and 2,201 control individuals through a two-stage genome-wide association study (GWAS)." (PMID 22737229, 2012). "In addition, our previous GWAS confirmed and identified the association of SNP markers located on HLA-DPA1 (rs3077) and HLA-DPB1 (rs9277535) genes with susceptibility to chronic hepatitis B (CHB) and HBV clearance in Japanese and Korean subjects." (PMID 24520320, 2014). "We also found that the HLA-DPA1 and HLA-DPB1 genes were significantly associated with protective effects against chronic hepatitis B (CHB) in Japanese, Korean and other Asian populations, including Chinese and Thai individuals (Pmeta = 4.40×10−19 for rs3077 and Pmeta = 1.28×10−15 for rs9277542)." (PMID 22737229, 2012). "Hence, we could confirm that the polymorphisms of HLA-DPA1 and HLA-DPB1 gene play a very important role in chronic hepatitis B virus infection in southern and northern Han Chinese populations." (PMID 21904616, 2011).
Sepsis (7 papers, 2021 to 2025). Sepsis is defined as life-threatening organ dysfunction caused by a dysregulated host response to infection. "A recent study suggests that HLA-DPA1 and -DRB3 are under-expressed in whole blood of sepsis patients caused by B. pseudomallei, which distinguished melioidosis from sepsis caused by other organisms." (PMID 33256556, 2021). "Gene expression analysis revealed a sepsis-associated decreased transcription of (i) the classical HLA genes HLA-DRA, HLA-DRB1, HLA-DPA1 and HLA-DPB1 and (ii) the gene of the MHC-II master regulator, CIITA (Class II Major Histocompatibility Complex Transactivator)." (PMID 33939725, 2021). "In contrast, sepsis Treg cells displayed four upregulated genes (RGS1, HLA-DPA1, BTG1, and GAPDH; 1.25, 1.02, 0.44, and 0.43log2FC, respectively)." (PMID 41208955, 2025). "As shown in these figures, the expression levels of RETN, S100A12, IL18R1, and KL were higher in the sepsis group, while that of GZMB, HLA-DPA1, CD3E, IL2RB, CD3G, and CCR3 were higher in the normal group (p < 0.05)." (PMID 38124071, 2023). "Our findings showed that the expression of RETN, S100A12, IL18R1, and KL was higher in the sepsis group, while the expression of GZMB, HLA-DPA1, CD3E, IL2RB, CD3G, and CCR3 was higher in the control group." (PMID 38124071, 2023). "Results of qRT-PCR validated the higher expression level of B2M as well as lower expression level of HLA-DQA1, HLA-DPA1, TAP1, and TAP2 in sepsis samples compared to control samples." (PMID 35685286, 2022). "Results of qRT-PCR validated the higher expression level of B2M as well as lower expression level of HLA-DQA1, HLA-DPA1, TAP1, and TAP2 in sepsis samples compared to control sample." (PMID 35685286, 2022). "Compared with healthy controls, B2M was significantly upregulated in sepsis samples yet the expression level of HLA-DQA1, HLA-DPA1, TAP1, and TAP2 was significantly lower in sepsis specimens." (PMID 35685286, 2022). "As an important finding, these interactions were confirmed for pairs of CTCF-sites and promoter regions of genes, which also displayed sepsis-induced alterations in our study (CM1 and HLA-DRA, CM2 and HLA-DRB1, CM9 and HLA-DPA1 and CM9 and HLA-DB1)." (PMID 33939725, 2021). "Similar to T cells and NK cells in sepsis, both naïve and switched resting B cell populations display significant decreases in the expression of several MHC-class II genes, including HLA-DRA, HLA-DRB1, HLA-DMA and HLA-DPA1." (PMID 41208955, 2025). "Additional experiments revealed that the observed elevation in CTCF expression, CTCF binding at CM1, CM2, CM3 and CM9 as well as the reduced expression of adjacent classical HLA genes HLA-DRA, HLA-DRB1, HLA-DPA1 and HLA-DPB1 persisted in all patients with postoperative sepsis." (PMID 33939725, 2021). "Even more importantly, the observed reduction in classical HLA-DRA, HLA-DRB1, HLA-DPA1 and HLA-DPB1 transcription as well as the decline in monocyte HLA-DR surface expression persisted in all patients with postoperative sepsis despite a recovery of CIITA transcription levels during the study period." (PMID 33939725, 2021).
type 1 diabetes (7 papers, 2011 to 2024). "Whereas in our pathway analysis, more genes are identified as part of Type I diabetes mellitus and Allograft rejection pathways (i.e. CD28, HLA-B, HLA-C, HLA-DMB, HLA-DPA1, HLA-DQA2, HLA-DRA, IL12A)." (PMID 22046267, 2011).
breast carcinoma (6 papers, 2009 to 2023). "Regarding the list for down regulated genes associated with breast cancer, 3 genes were also present in our list (HLA-DPA1, PCDH9 and NCALD)." (PMID 29108258, 2017).
diabetes (6 papers, 2008 to 2023). "Previous studies have shown that HLA-DPA1, the closest centromere gene expressed in HLA-DO α, may increase the risk of diabetes and diabetic kidney disease (DKD), which is a complication of diabetes." (PMID 37250717, 2023). "Moreover, the HLA subtypes HLA-A*11:01, HLA-B*46:01, HLA-DPA1*01:03, and HLA-DPB1*05:01 were associated with heart disease, stroke, diabetes, and hypertension among subjects with GD." (PMID 35321340, 2022). "Moreover, the HLA subtypes HLA-A*11:01, HLA-B*46:01, HLA-DPA1*01:03, and HLA-DPB1*05:01 were found to be associated with heart disease, stroke, diabetes, and hypertension among subjects with GD." (PMID 35321340, 2022). "On the other hand, genotypes HLA-DPA1*01:03-DPA1*01:03 and DPA1*01:03-DPA1*02:01 were significantly more frequent among the subjects with GD and diabetes than in those with GD without diabetes." (PMID 37841270, 2023). "A higher percentage of HLA-DPA1*01:03-*01:03 (7.2% vs. 3.7%, P value = 0.006) and *01:03-*02:01 (4.9% vs. 2.3%, P value = 0.009) genotypes were identified among the subjects with GD that had diabetes than those with GD that did not have diabetes." (PMID 35321340, 2022).
autoimmune disease (5 papers, 2020 to 2024). A disorder resulting from loss of function or tissue destruction of an organ or multiple organs, arising from humoral or cellular immune responses of the individual to their own tissue constituents. "Polymorphisms in the HLA-DMB and HLA-DPA1 genes have been linked to autoimmune diseases like rheumatoid arthritis and psoriasis." (PMID 38835033, 2024). "Key mutations in HLA-DPA1 are associated with genetic susceptibility to rare autoimmune diseases, such as granulomatosis with polyangiitis." (PMID 38665582, 2024).
ovarian carcinoma (5 papers, 2020 to 2024). A malignant neoplasm originating from the surface ovarian epithelium. "Major Histocompatibility Complex molecule also close to CX3XR1 expression in epithelial ovarian cancer, like HLA-DMA (R = 0.49, P < 2.2e−16) and HLA-DPA1 (R = 0.473, P < 2.2e−16)." (PMID 38241595, 2024). "MSLN was positively correlated with immunosuppressive genes in ovarian cancer, such as LGALS9, CD276, TMIGD2, CD200, TNFRSF14, and human leukocyte antigen (HLA)-related families including HLA-DRA, HLA-DRB1, HLA-DPA1, HLA-DMA, HLA-E, etc.." (PMID 35692779, 2022). "Besides, MHC molecules, including HLA-B (cor = 0.365, p = 5.69e-11), HLA-DMA (cor = 0.413, p = 7.02e-14), HLA-DPA1 (cor = 0.475, p = 2.03e-18), HLA-DQA1 (cor = 0.467, p = 8.07e-18), and HLA-E (cor = 0.447, p = 2.6e-16), were significantly correlated with the expression of SUCNR1 in ovarian cancer." (PMID 33062639, 2020).
asthma (4 papers, 2011 to 2026). "We determined HLA-DPA1 genotypes by using direct sequencing and MACH imputation of the data from 1135 cases and 2376 controls and found that DPA1*0201 was strongly associated with pediatric asthma (P = 5.2×10−10, OR = 1.52)." (PMID 21814517, 2011). "SNP rs987870, located between HLA-DPA1 and HLA-DPB1, was consistently associated with pediatric asthma in 3 independent populations (Pcombined = 2.3×10−10, odds ratio [OR] = 1.40)." (PMID 21814517, 2011). "Grass pollen allergy is not a major cause of asthma in Japan; therefore, the HLA-DPA1*0201 association in the present study was less likely to be due to sensitization to grass pollen." (PMID 21814517, 2011).
lung adenocarcinoma (4 papers, 2019 to 2025). A carcinoma that arises from the lung and is characterized by the presence of malignant glandular epithelial cells. "The objective of this study was to comprehensively analyze the roles of HLA-DPA1 and its association with lung adenocarcinoma (LUAD)." (PMID 37899135, 2023). "The top genes of activated neutrophils, namely HLA‐DPA1, HLA‐DRA, and HLA‐DRB1, were found to be associated with a good prognosis in lung adenocarcinoma (LUAD)." (PMID 38483933, 2024). "In lung adenocarcinoma, high expression of CCL20, IL23A, MMP1 and MMP3 was significantly associated with poor patient prognosis, whereas high expression of FOS, HLA-DPA1, HLA-DPB1, HLA-DQA1, HLA-DQB1 and HLA-DRA was significantly associated with improved patient prognosis." (PMID 40016789, 2025). "For both HLA-DPA1 and HLA-DRA, the rank of correlations is highest in cutaneous melanoma, followed by lung adenocarcinoma, sarcoma and breast invasive carcinoma." (PMID 31212865, 2019).
cervical cancer (3 papers, 2017 to 2022). A primary or metastatic malignant neoplasm involving the cervix. "Recently, a number of genome-wide association studies (GWAS) have been performed to investigate the association between specific HLA II alleles and cervical cancer in Asia and Europe, and many case-control studies have reported the association of HLA-DPA1, DPB1, and DPB2 with cervical cancer." (PMID 30009173, 2018).
cutaneous melanoma (3 papers, 2019 to 2024). A primary melanoma arising from atypical melanocytes in the skin. "HLA-DPA1 is the 80th gene most closely correlated with survival in cutaneous melanoma, although the expression level of HLA-DPA1 in cutaneous melanoma was not the highest among 21 common cancer types." (PMID 31212865, 2019). "Using the Oncomine database and cBioPortal for public microarray data of cutaneous melanoma, we selected three datasets composed of melanoma tumor samples to analyze the genes co-expressed with HLA class II genes, specifically HLA-DPA1 and HLA-DRA." (PMID 31212865, 2019). "HLA-DPA1 was found to be the 80th most closely correlated gene with cutaneous melanoma." (PMID 39763976, 2024). "A previous study revealed that the expression level of HLA-DPA1 was higher in tumor tissues than that in normal tissues and patients with the high level of HLA-DPA1 had a good prognosis in skin cutaneous melanoma." (PMID 36627705, 2023).
hepatitis B virus infection (3 papers, 2012 to 2016). A viral infection caused by the hepatitis B virus. "Patients failing to produce proper MHC II–peptide complexes do not mount efficient antibody responses to infection, and this is probably the underlying factor in differential hepatitis B viral resistance shown in association studies of HLA-DPA1." (PMID 26998349, 2016). "We performed trans-ethnic association analyses of HLA-DPA1, HLA-DPB1 alleles and haplotypes with hepatitis B virus infection and disease progression among Asian populations comprising Japanese, Korean, Hong Kong, and Thai subjects." (PMID 24520320, 2014).
hepatocellular carcinoma (3 papers, 2015 to 2024). A malignant tumor that arises from hepatocytes. "In the field of cancer, HLA-DPA1 activates chemokines and toll-like receptor signaling pathways to regulate hepatocellular carcinoma progression." (PMID 36245844, 2022).
melanoma (3 papers, 2011 to 2025). A malignant, usually aggressive tumor composed of atypical, neoplastic melanocytes. "Other research found that class II molecules (HLA-DPA1, HLA-DPB1, HLA-DQA1, HLA-DRA, HLA-DRB1, HLA-DRB5) are important biomarkers in the occurrence and progression of melanoma tumors, and their expression levels are closely related to prognosis and immune infiltration." (PMID 39969704, 2025).
multiple myeloma (3 papers, 2020 to 2025). "Lower expression of HLA-DPA1 expression is associated with a poor prognosis in patients with multiple myeloma and adrenal cortical tumors." (PMID 40165344, 2025). "RGS1 can impair Treg migration, the class II HLA-DPA1 has been associated with hypoxia in multiple myeloma." (PMID 41208955, 2025).
viral infections (3 papers, 2016 to 2024). "In humans, specific alleles of the HLA-DPA1, HLA-DQA1 and HLA-DRB1 loci have been associated with viral infections." (PMID 27812212, 2016).